NOTCH1 (notch receptor 1)
Diseases named in the same sentence as NOTCH1 in open-access papers (continued):
Sharing a sentence is not in itself a finding about the gene and the disease.
tumor (continued). "For this reason, we studied this dual activity of NOTCH1 in arsenic-induced keratinocyte transformation, thus providing a model to investigate the molecular aspects determining whether NOTCH signaling will be either oncogenic or tumor-suppressive." (PMID 31597699, 2019). "In conclusion, our study substantiates the role of AKT and Notch1 in cell proliferation, angiogenesis, and EMT of CRC cells and demonstrates that VJ may be a viable therapeutic option to counter AKT-induced cell proliferation and tumor outgrowth in CRC." (PMID 30038258, 2018). "Furthermore, we found that Notch2 is the major driver of the biliary phenotype in AKT/Yap tumors, whereas inactivation of Notch1 slightly delays tumor development without affecting the histological features of AKT/Yap ICC lesions." (PMID 29545603, 2018). "To determine whether tumour cell lines can induce NOTCH1 signalling and repress HMGAs non-autonomously, we repeated the co-cultures and isolated the IMR90 ER:HRASG12V mRFP1 cells using flow cytometry." (PMID 29743479, 2018). "Indeed, in the stromal regions of the primary tumour, the vascular expression of cleaved NOTCH1 (NOTCH1 intracellular domain, NICD, indicates active NOTCH1 signalling) correlated with FABP4 expression, whereas in vessels within the tumour and the tumour–stroma interface this correlation was lost." (PMID 27568980, 2017). "To examine whether an association could be established in vivo between the P. gingivalis–induced activation of Notch1 and chemoresistance demonstrated in vitro, we monitored the NICD levels in tumor xenografts with P. gingivalis–infected and control OSC-20 cells." (PMID 28388583, 2017). "Interestingly, the only Lck-Dlx5 tumor (1/11) without overexpression of Notch1 and Notch3 instead showed upregulation of Notch2, further suggesting an essential role for aberrant Notch signaling in Dlx5-driven T-cell lymphomagenesis." (PMID 28122332, 2017). "Thus, Notch1 activation is essential for the induction of CD44H cells while it may be dispensable for their maintenance and tumor initiation by CD44H cells." (PMID 29170450, 2017). "Targeting NOTCH1 in HNSCC may simultaneously reduce both CSCs and tumor neo-angiogenesis." (PMID 27108536, 2016). "In the absence of estradiol, the tumor-promoting effect of Notch1 was almost lost." (PMID 27281612, 2016). "Interestingly, western blot analysis showed higher Notch1 expression in the non-tumor liver of rats that developed HCC nodules compared to those that did not develop tumors suggesting a role of Notch1 in HCC development." (PMID 27167202, 2016). "Paralog-specific effects may be prominent in these tumors, and there is some preliminary evidence that Notch1 and perhaps Notch3 act as a tumor suppressors in some of NETs but not in others." (PMID 27148486, 2016). "Together with our genetic observations, these functional data indicate that NOTCH1 may act as a tumor suppressor via regulating tumor growth but not metastasis in ESCC." (PMID 26528858, 2016). "Indeed, DAPT could decrease NOTCH1 and HES1, which indicates that the decrease of tumor size in nude mice by DAPT is an on-target effect." (PMID 27108536, 2016). "For instance, conditional deletion of Notch1 in mouse skin epidermis 88 or hair follicles stem cells 89 leads to overactivation of the WNT/β‐catenin pathway and induction of tumors in a noncell autonomous manner (i.e., the tumor cells are wild type for Notch1)." (PMID 26763580, 2016). "In addition, it was also found that p21CIP1, involved in regulation of cellular senescence, functions as a negative transcriptional regulator of WNT4 downstream of Notch 1 and that p21CIP1 potentially reorganizes the nucleus during tumour reversion." (PMID 25821840, 2015).
tumor (continued). "Examples of known enhancers that displayed DNA methylation changes in these clusters include the tumor-specific hypomethylation of the distal enhancer of MYC (C-5 HMR) that is 67 Kb upstream of the TSS, and the hypermethylation of the enhancer in the second intron of NOTCH1 (A-7 HMR)." (PMID 25706888, 2015). "Furthermore, siRNA-mediated knock-down of Notch1 or Notch2 impaired tumor formation in xenografts but unfortunately, GSIs were not tested in this setting." (PMID 25601901, 2014). "Furthermore, the absent staining of TRAP and positive staining of CD31 in multinucleated giant cells suggest that these cells are not osteoclasts, but rather a type of angiogenic tumor cells in which ADAM10/Notch1 signaling is activated." (PMID 24548763, 2014). "Additional evidences are also suggestive of a tumor suppressor function of Notch in PC, including the observations of downregulation of HEY1 and of activated Notch1, and prevention of luminal cell differentiation and induction of proliferation in Notch1 knock-out models." (PMID 24684754, 2014). "Moreover, a critical role of Notch-4 rather than Notch1 has been recently shown for the survival of tumour-initiating cells." (PMID 24919951, 2014). "We found no changes in tumor weight, or apoptosis as a result of silencing Notch1." (PMID 24066611, 2013). "Immunostaining revealed that shN1 did not affect Notch1 activation in the tumor blood vessels." (PMID 24066611, 2013). "In the tumor samples, rather homogeneous staining could be seen in the poorly differentiated tumors, while the well differentiated tumors were mainly positive in their basal layers of the tumor nests, and some tumors were negative for Notch1 expression." (PMID 23409141, 2013). "Taking into consideration that CD44 is a transcriptional target of Notch-1, apparently downstream of Hes1/Hey1, we concluded that β-elemene could attenuate tumor angiogenesis by targeting GCSCs at least in part through Notch-1 expression." (PMID 23710217, 2013). "Notch1 and Notch4 are expressed in normal and tumor lymphatic endothelial cells, and Notch1 is activated in lymphatic endothelium of invasive mammary micropapillary carcinomas These data suggest a role for cross-talk between VEGFR-3 and Notch in both tumor angiogenesis and lymphangiogenesis." (PMID 22487493, 2012). "Of note, the selection of tumour initiating cells by this in vivo assay resulted in enrichment of these stem cell markers, over baseline levels in vitro, where differences were 11-fold, 80-fold, 44-fold and 140-fold for ABCG2, Nanog, Notch1 and SOX2 expression, respectively (p<0.05)." (PMID 23226356, 2012). "However, disease recurred within 21 days in 2 tumor bearing mice treated with dox, suggesting that NOTCH1 inhibition in these tumors was not sufficient to eliminate the tumor-initiating cells." (PMID 22992387, 2012). "Interestingly, in our model expression of human intracellular NOTCH1 in the developing mouse mammary gland did not result in induction of diverse tumor types that regressed upon weaning." (PMID 22992387, 2012). "Additionally, we investigated a potential non-cell autonomous function of Notch1 using an orthotopic transplantation tumor model." (PMID 23284900, 2012). "Our findings demonstrate that high NF-κB and low Notch1 expression are correlated with high expression of VEGFR-3 (a marker of LVD) and VEGF-C, in ESCC patients, revealing an inverse relationship between Notch1 and NF-κB signaling and tumor-induced lymphangiogenesis." (PMID 21939555, 2011). "The hypothesis of USP28 as an oncogenic regulator in CLL is additionally supported by our observation that NOTCH1 signaling is not upregulated in CLL cells with del(11q) as it would have been expected in a simplistic model of the tumor suppressor mechanism in 11q." (PMID 40456839, 2025).
tumor (continued). "Therefore, beyond the potential role of NOTCH1 in early stages of oral tumorigenesis, it could also be involved in disease progression, thus acting as an oncogene rather than a tumor suppressor." (PMID 41009728, 2025). "In addition, the reductions in CD133‐positive tumour cells and Notch1 protein in UCHL1‐knockdown PDOs could not be restored by DETA NONOate treatment, confirming the Notch1 deubiquitylation and CSC maintenance as downstream consequences of NO metabolism." (PMID 39523215, 2024). "However, tumor-suppressing mechanisms of NOTCH1 signaling are not entirely understood." (PMID 38706595, 2024). "Also, increased levels of markers such as TIGIT, Nrp-1, neurogenic locus notch-homolog protein 1 (Notch-1), T cell immunoglobulin and mucin domain 3 (TIM-3), B-lymphocyte-induced maturation protein 1 (BLIMP-1) and others also contribute to enhanced Treg activity and the promotion of tumor growth." (PMID 38891091, 2024). "However, post‐radiotherapy treatment of the organoids with L‐NAME led to a decrease in both the proportion of CD133‐positive tumour cells and Notch1 protein levels, indicating that NO regulation could control the CSC pool by targeting Notch1 protein in NSCLC PDOs." (PMID 39523215, 2024). "An important finding from our in vivo study is that although neither Notch1 nor Notch2 acts as a tumor suppressor to fully substitute Pten in BRFAV600E induced melanomagenesis, the loss/decrease of Notch proteins appeared to accelerate tumor formation and promote tumor growth." (PMID 36672468, 2023). "Indeed, OMP-A2G1 alone inhibited tumor growth to a greater extent than docetaxel alone, which inspires the thought that specific Notch1 inhibition may not be sufficient to potentiate taxanes’ therapeutic effect in this cancer." (PMID 34680255, 2021). "Further, in patients-derived cells, silencing of Notch 1 or Notch 2 does not counter resistance to β-catenin inhibition, rather pharmacological pan-Notch inhibition is needed to overcome resistance and its effect on in vitro tumor sphere formations as well as in vivo liver metastases." (PMID 34179007, 2021). "In addition, our study found that Notch1 was significantly inactivated in the presence of DCLK1 knockdown, which was consistent with the previous study, indicating that DCLK1 may regulate tumour metastasis and the EMT process of GC via mediation of the Notch1 signalling pathway." (PMID 32423385, 2020). "To follow up on these findings, suggesting that Notch1, and possibly also Notch2 may be connected to the cytokine-stimulated integrative system that we study in TNBC, we next used the TCGA dataset to analyze the relevance of Notch1 and Notch2 to the tumor-stroma-inflammation network." (PMID 31105691, 2019). "Interestingly, decreased levels of Notch4 (but not of Notch1), obtained by both RNA interference or pharmacological treatment, significantly reduced mammosphere formation in vitro and reduced tumor formation in vivo, thus suggesting a specific role of Notch4 in regulating this subpopulation." (PMID 31379945, 2019). "However, substantial Notch1 expression could still be observed in AKT/Yap/Cre tumors, suggesting that most of Notch1 was not expressed in tumor cells, but in other cell types within the ICC lesions." (PMID 29545603, 2018). "Therefore, the GSI pretreatment could reduce the acquisition of EMT and inhibit the activation of Notch1 and Snail, which induced the transplanted cells to undergo neuronal maturation without tumor-like overgrowth upon transplantation of hiPSC-NS/PCs for SCI." (PMID 27666789, 2016). "However, owing to the potential tumor suppressing roles rather than the oncogenic function of NOTCH1 in ESCC, targeting NOTCH signaling might not be helpful for treating ESCC." (PMID 26528858, 2016). "Finally, we uncovered that the lack of Notch1 expression could inhibit tumor's development in vivo contributing to the “field effect”." (PMID 27167202, 2016).
tumor (continued). "Several studies have shown that Notch1 signaling might be involved in regulating tumor progression through interacting with multiple signaling pathways, including PI3K/AKT, NF-κB and Wnt pathway, but further studies were needed to identify the functions and mechanisms of Notch1 signaling in PTC." (PMID 25887589, 2015). "Furthermore, Notch mutation study of head and neck squamous cell carcinomas also suggests that Notch1 may function as a tumor suppressor gene rather than an oncogene in this tumor." (PMID 23409141, 2013). "Finally, we investigated whether Notch1 functions through a non-cell autonomous mechanism to suppress tumor maintenance using an orthotopic transplantation model." (PMID 23284900, 2012). "Our study reports a previously unrecognized epidermal expression of PDX1 and adds further evidence for a pivotal role of Notch1 but not Notch2 as a tumor suppressor in the skin, which may be particularly interesting in the light of new therapeutic approaches targeting single Notch receptors." (PMID 21042537, 2010). "The int-CAs showed higher expression of IR transcripts of NOTCH1 and NOTCH3 compared to the other tumor types but did not have the IR transcripts of NOTCH2 and NOTCH4 (p < 0.05)." (PMID 39101773, 2024). "In 370 HCC samples, the expression levels of Notch 1, Notch 2, Notch 3, Notch 4, DLL4, JAG1, and JAG2 were markedly greater in tumor samples compared to surrounding non-tumorous tissue." (PMID 38816668, 2024). "However, stem and progenitor cells in non-pathological intestinal regions, as well as in tumor cells, undergo differentiation into goblet cells following inhibition of NOTCH1/HES1 signaling, a non-specific targeting of these pathways could cause severe side effects." (PMID 37860822, 2023). "Further, it effectively inhibited tumor growth in control (pCMV/HCT116) and Notch1/HCT116 xenotransplanted mice without any apparent systemic toxicity." (PMID 35164150, 2022). "Our results indicate that Crenigacestat significantly inhibited NOTCH1 and HES1, whereas tumor progression was not affected." (PMID 35457006, 2022). "The more profound effects on the migration and EMT of tumour cells by DBZ than by Tspan5 itself were not surprising, as the γ‐secretase complex would act on all four Notch receptors (Notch1–4) and perhaps other proteins in HCC cells." (PMID 33955149, 2021). "HCC patients with TNM stage III–IV and tumor vein invasion had higher levels of Notch1 expression compared with patients with TNM stage I–II and patients without tumor vein invasion." (PMID 34988028, 2021). "The binding of ASR490 with NRR resulted in significant inhibition of activated Notch1 signaling and abrogated CRC cell growth and tumor growth in xenograft models (data not published)." (PMID 32630477, 2020). "5-Aza-CdR interestingly decreased levels of genes that promote tumor progression, such as CCND1, MKI67, BIRC5, and BCL2, but failed to decrease MUC4 and NOTCH1." (PMID 32182826, 2020). "Cell-specific analyses complemented these results by indicating that NOTCH1, NOTCH2 and NOTCH3 were up-regulated by TNFα in the tumor cells but not in the MSCs." (PMID 31105691, 2019). "Interestingly, the expressions of NOTCH1, NOTCH2 or NOTCH3 are highly correlated with those of many prognostic immune receptors, implying that Notch signaling might be important in the regulation of tumor immune response or tumor microenvironment, which, in fact, has been reported in many studies." (PMID 31185958, 2019). "Enhanced tumor growth was observed in the CAM assay after Notch2 ICD, but not Notch1 ICD, expression." (PMID 29993038, 2018). "Compared with nontumor normal tissues, downregulation of Notch1 and Notch4 was observed in HCC tissues, while Notch2 expression was not significantly different between tumor and normal tissues." (PMID 28568708, 2017).
tumor (continued). "In agreement with our results, a study found that Notch1 expression was inversely correlated with stage, despite lack of correlative data on nodal metastasis, in 395 NSCLC tumor samples by immunohistochemistry using a semi-quantitative scoring method." (PMID 25653136, 2015). "This study also demonstrates that the multinucleated giant cell is an angiogenic tumor cell, rather than an osteoclast, and involves ADAM10/Notch1 signaling activation." (PMID 24548763, 2014). "To validate the DASL observations, we performed quantitative RT-PCR on the representative upregulated genes, and observed that the expression of mRNAs, including MMP7, NOTCH1, FZD7, were significantly higher in TN tumor samples than in non-TN tumor samples." (PMID 24143235, 2013). "The mRNA levels for several critical components of the pathway (BIRC5, CD44, FZD7, c-MET, MMP7, c-MYC, NOTCH1, PPARD, and VEGF) were significantly increased (DASL signal intensity) in TN tumor samples as compared to non-TN tumor samples." (PMID 24143235, 2013). "Differences in LVD status were significantly correlated with expression of NF-κB, Notch1 and VEGF-C, independent of T stage, sex, age, and differentiation status of tumor cells." (PMID 21939555, 2011). "The group exhibiting low NOTCH1 expression levels comprised a significantly higher proportion of individuals with TNM stage M0 (p=0.0021), suggesting an absence of metastatic activity in the tumor." (PMID 39737401, 2024). "It is worth noting that the correlation between SUV39H1 and NOTCH1 and MVD is weak, which may indicate that SUV39H1 may not be directly involved in tumor angiogenesis in OSCC." (PMID 38650654, 2024). "In addition, the expression level of NOTCH1 and PITX1 was lower in the tumor tissue of smoking patients compared to the tumor tissue of nonsmoking patients." (PMID 38540309, 2024). "Moreover, NOTCH1-mutant but GSI-resistant T-ALLs demand the implementation of alternative strategies that efficiently and safely target NOTCH1-dependent tumor cells without detrimental effects." (PMID 36674902, 2023). "In addition, ASR490 inhibited the tumor growth in control (pCMV/HCT116) and Notch1/HCT116 xenotransplanted mice without any apparent systemic toxicity." (PMID 35164150, 2022). "Nevertheless, the depletion of NOTCH1 in HNSCC cell lines resulted, not surprisingly, in down-regulation of Notch-target genes such as c-Myc, and to reduced EMT-like phenotypes, such as lower tumour cell motility and invasion." (PMID 34944837, 2021). "In addition, overall RNA levels of Notch1, CDX2 and miR-181a were increased in tumor samples relative to non-cancerous tissues (median FC = 2.742, 3.47 and 1.5, respectively)." (PMID 32704077, 2020). "During neoplastic progression, tumour cells generate mechanisms to survive the negative effects of hypoxia, one of which is the activation and stabilisation of the transcriptional activity of HIF-1α, which can then regulate the NOTCH1 signalling pathway." (PMID 32386517, 2020). "Noticeably, this latter work also disclosed that unlike Notch1 or Notch3, which displayed increased levels, Notch2 was decreased in advanced tumors in the KrasG12D NSCLC model, where it furthermore displayed a tumor suppressor function through modulation of the Wnt/β-catenin pathway." (PMID 32784481, 2020). "Interestingly, unlike Notch1, Ikaros and IRF8 expressions were found to be significantly elevated in the “stunted” DN2-T cells isolated from the thymi of tumor-bearing mice." (PMID 32582141, 2020). "Additionally, none of the putative tumor-suppressor genes relevant to LGG, namely, ATRX, CIC, FUBP1, and NOTCH1, showed correlations with overall survival (data not shown)." (PMID 27852048, 2017). "This may be due to p21 inhibiting cellular growth by pathways not regulating cell cycle, for instance, during notch 1 activation, p21 suppressed E2F1-dependent Wnt4 expression to inhibit tumor cell proliferation." (PMID 28522974, 2017).